RNU6-111P (RNA, U6 small nuclear 111, pseudogene)
Gene: Small nuclear RNA gene on chromosome 2 (73,298,683 to 73,298,787, forward strand). Ensembl gene ENSG00000252988.
Homologues: Orthologues: chimpanzee U6 (98% identical), mouse Gm25599 (60% identical). Paralogues in human: RNU6-829P (74% identical), RNU6-406P (73% identical), RNU6-199P (72% identical), RNU6-455P (72% identical), RNU6-1152P (71% identical), RNU6-116P (71% identical), RNU6-1266P (71% identical), RNU6-43P (71% identical), RNU6-595P (71% identical), RNU6-1009P (70% identical), RNU6-1048P (70% identical), RNU6-1060P (70% identical), and 1284 more.